TXNIP (thioredoxin interacting protein)
Description:
May act as an oxidative stress mediator by inhibiting thioredoxin activity or by limiting its bioavailability. Interacts with COPS5 and restores COPS5-induced suppression of CDKN1B stability, blocking the COPS5-mediated translocation of CDKN1B from the nucleus to the cytoplasm (By similarity). Functions as a transcriptional repressor, possibly by acting as a bridge molecule between transcription factors and corepressor complexes, and over-expression will induce G0/G1 cell cycle arrest. Required for the maturation of natural killer cells (By similarity). Acts as a suppressor of tumor cell growth. Inhibits the proteasomal degradation of DDIT4, and thereby contributes to the inhibition of the mammalian target of rapamycin complex 1 (mTORC1).
Synonyms: VDUP1; EST01027; HHCPA78; THIF; ARRDC6
Tractability: Antibody: the Human Protein Atlas places it where antibodies can reach. PROTAC: UniProt records ubiquitination sites on it; ubiquitination databases record sites on it; its protein half-life has been measured.
Gene: Protein-coding gene on chromosome 1 (145,992,435 to 145,996,580, reverse strand). Ensembl gene ENSG00000265972.
Subcellular location: Cytoplasm; Nucleus
Subcellular location (Human Protein Atlas): Plasma membrane; Cytosol
Pathways (Reactome):
Cellular responses to stimuli: Cytoprotection by HMOX1
Disease: Purinergic signaling in leishmaniasis infection
Gene expression (Transcription): Regulation of FOXO transcriptional activity by acetylation
Immune System: The NLRP3 inflammasome
Gene Ontology:
Molecular function: enzyme inhibitor activity; protein binding; ubiquitin protein ligase binding; molecular adaptor activity
Biological process: cellular response to tumor cell; keratinocyte differentiation; negative regulation of cell division; response to oxidative stress; cellular response to oxidised low-density lipoprotein particle stimulus; inflammatory response; positive regulation of apoptotic process; regulation of cell population proliferation; response to calcium ion; response to estradiol; response to glucose; response to hydrogen peroxide; response to mechanical stimulus; response to progesterone; response to xenobiotic stimulus
Cellular component: cytoplasm; nucleus; cytosol
Genetic constraint (gnomAD): Loss-of-function variants: 23 observed, 45.94 expected, observed/expected ratio (o/e) 0.5, 90% interval 0.36 to 0.71. The synonymous counts are far from expectation, so gnomAD's model fits this gene poorly and the ratio says little. Missense variants: 555 observed, 514.89 expected, observed/expected ratio (o/e) 1.08, 90% interval 1 to 1.16. Synonymous variants: 234 observed, 183.06 expected, observed/expected ratio (o/e) 1.28, 90% interval 1.15 to 1.42.
Homologues: Orthologues: chimpanzee TXNIP (99% identical), macaque TXNIP (99% identical), dog TXNIP (98% identical), rat Txnip (97% identical), pig TXNIP (97% identical), mouse Txnip (96% identical), rabbit TXNIP (95% identical), guinea pig TXNIP (93% identical), tropical clawed frog txnip (76% identical), zebrafish txnipa (60% identical), zebrafish txnipb (52% identical), Caenorhabditis elegans arrd-16 (23% identical), and 10 more. Paralogues in human: ARRDC4 (44% identical), ARRDC3 (42% identical), ARRDC2 (38% identical), ARRDC1 (21% identical), ARRDC5 (16% identical).
Diseases named in the same sentence as TXNIP in open-access papers:
TXNIP is named in the same sentence as 318 diseases in open-access papers, as found by Europe PMC text mining. Sharing a sentence is not in itself a finding about the gene and the disease. The quoted sentences say what the papers report.
diabetes (221 papers, 2007 to 2026). "TXNIP elevated levels are found in patients with diabetes and chronic hyperglycemia, and this is closely linked to the onset of diabetes and its complications." (PMID 41457140, 2025). "Instead, RFX3 loss increased TXNIP, a pro-apoptotic protein linked to diabetes and oxidative stress-induced beta cell death." (PMID 40263183, 2025). "Several authors have investigated polymorphisms in the TXNRD2 and TXNIP and DN, as well as other complications related to diabetes." (PMID 40076459, 2025). "TXNIP-mediated redox inhibition was associated with the premature death of insulin-secreting cells in patients with diabetes." (PMID 38397668, 2024). "Scholars have identified associations between TXNIP and several conditions, including cancer, atherosclerosis, diabetes and its complications, neurodegenerative and cerebrovascular diseases such as Alzheimer’s disease, stroke, and subarachnoid hemorrhage." (PMID 39330495, 2024). "Elevated levels of TXNIP are found in human diabetic islets and induce β-cell apoptosis, whereas β-cell-specific TXNIP deficiency protected against diabetes in NOD and streptozotocin-induced mouse models." (PMID 38308004, 2024). "Whole body TXNIP deficiency and beta cell specific TXNIP deletion have been shown to protect mice against diabetes in models of T1D and T2D including streptozotocin (STZ)-induced beta cell destruction and genetic obesity and insulin resistance." (PMID 39429740, 2024). "In diabetic patients, increased TXNIP expression has been linked to changes in the kidney architecture and function in both diabetes patients and animals." (PMID 38138443, 2023). "TXNIP is linked to oxidative stress; TXNIP methylation in blood is associated with future T2D27, and we found lower TXNIP methylation in the severe insulin-deficient diabetes subgroup of T2D50." (PMID 38086799, 2023). "TXNIP is associated with diabetes mellitus, specifically T2DM, and regulates diabetes-related cellular functions such as glucose homeostasis, insulin resistance, and pancreatic β cell function." (PMID 38137029, 2023). "Thioredoxin-interacting protein (TXNIP) is elevated in diabetes and obesity and has been linked to NLRP3 inflammasome activation." (PMID 36670488, 2023). "TXNIP has been implicated in the development of several diseases, including cancer, diabetes, and cardiovascular disease." (PMID 37240157, 2023). "Our DMP analysis identified cg19693031 as the most significant DMP associated with diabetes, and cg26964062, located within TXNIP, was sequentially identified as an important CpG site." (PMID 38137029, 2023). "Studies in humans have shown that TXNIP is associated with diabetes and is able to regulate the peripheral glucose metabolism." (PMID 36733403, 2023). "These notions are supported by cumulative evidence that loss of TXNIP by pharmacological inhibition or genetic perturbations results in amelioration from neurological disease and diabetes in murine models." (PMID 37794178, 2023). "The study was initiated to get an insight into the interaction tendency of P. granatum derived compounds with diabetes associated human thioredoxin-interacting protein (TXNIP)." (PMID 39319322, 2023). "The master roles of TXNIP in fasting, insulin sensitivity, and β-cell apoptosis are well known, and these functions have been linked to an increased risk of diabetes and other metabolic disorders." (PMID 37794178, 2023). "Many studies have suggested that TXNIP plays an important role in the onset and progression of diabetes, and TXNIP epigenetic regulation is linked to diabetes prevalence." (PMID 37144033, 2023). "Several epigenome-wide association studies (EWAS) on methylation have identified TXNIP cg19693031 as the top diabetes-related methylation site." (PMID 35164795, 2022). "Thioredoxin-Interacting Protein (TXNIP) has been shown to have significant pathogenic roles in many human diseases, particularly those associated with diabetes and hyperglycemia." (PMID 39483368, 2022).
diabetes (continued). "Both hypoxia and oxidative stress/ROS induce thioredoxin-interacting protein (Txnip), a major cause of β-cell dysfunction in diabetes." (PMID 35557947, 2022). "Further, TXNIP has been implicated in the development of diabetes-induced complications, including coronary heart disease." (PMID 35456489, 2022). "Altered TXNIP activity has been implicated in the development of several diseases aside from diabetes, including atherosclerosis, cancer and neurodegenerative diseases." (PMID 35456489, 2022). "In fact, TXNIP is considered a key factor in diabetes-associated beta cell apoptosis and genetic deletion of TXNIP has been shown to mimic the anti-diabetic effects of verapamil in different mouse models." (PMID 35241690, 2022). "Many experimental studies have demonstrated an increase in ASK1 induced by TXNIP, which is associated with retinal neurodegeneration and diabetes." (PMID 36017183, 2022). "Thioredoxin-interacting protein (TXNIP) has emerged as a key pathological regulator of various diseases, associated with glucose and lipid abnormalities and inflammation, including diabetes mellitus and cerebrovascular diseases." (PMID 34681207, 2021). "For example, carotid artery intima-media thickness is used as an indicator of atherosclerosis in patients with early-stage diabetes, and impaired glucose tolerance and is associated with increased plasma levels of TXNIP." (PMID 33567593, 2021). "Thioredoxin-interacting protein (TXNIP) plays an important role in the redox system, but it is implicated differently in many diseases, including cancers, diabetes, and neurodegenerative disorders." (PMID 34500775, 2021). "Another ROS-redox-sensitive factor TXNIP is found to be associated with enhanced oxidative stress and inflammation leading to atherosclerosis in ApoE KO mouse model of diabetes." (PMID 34829831, 2021). "In fact, the inhibition of TXNIP expression using fenofibrate treatment also helps to counter the post-ischemic revascularization defect of the lower limbs associated with diabetes." (PMID 33567593, 2021). "Chronic hyperglycemia has long been associated with brain endothelial complications in diabetes and metabolic disorders through different signaling cascades, including the TXNIP/NLRP-3 pathway." (PMID 34681207, 2021). "Elevated TXNIP is implicated in the pathogenesis of various complex diseases, including diabetes and neurologic and inflammatory disorders." (PMID 34944690, 2021). "Thioredoxin-interacting protein (TXNIP) has been linked to the promotion of diabetes and its vascular pathological effects." (PMID 32256950, 2020). "TXNIP was linked with dysregulation in β-cells, peripheral tissues for diabetes, and dopaminergic neurons, especially under high glucose conditions." (PMID 32824669, 2020). "NLRP3, IL-1β, reactive oxygen species (ROS), and TXNIP are implicated in the type 2 diabetes mellitus (T2DM) pathogenesis." (PMID 32187211, 2020). "It has been demonstrated that TXNIP is up-regulated in diabetes, ischemia, and hypertension, which were risk diseases for AD." (PMID 32309439, 2020). "Intriguingly, accumulating evidence indicates that TXNIP is associated with glucose metabolism and diabetes." (PMID 32973739, 2020). "TXNIP is involved in vascular dysfunction due to damage to vessel endothelial cells, the major cause of complications resulting from diabetes." (PMID 33302545, 2020). "We will also consider the evidence for the pathological contribution of diabetes and diabetes-induced oxidative stress to Alzheimer’s disease (AD) as part of this review, and how it can be linked to TXNIP." (PMID 33302545, 2020). "Other studies have determined that individuals who carry the T allele of the rs7211 polymorphism in the TXNIP gene present with higher plasma triglycerides levels, impaired glucose homeostasis, and increased risk of diabetes." (PMID 31372175, 2019).
diabetes (continued). "Meanwhile, the increase of TXNIP expression by selective loss of mechanistic target of rapamycin (mTOR) in mouse β-cells exacerbates the development of diabetes." (PMID 31623194, 2019). "TXNIP is linked to increased oxidative stress, along with fibrosis and arrhythmias in diabetes, as well as diabetic cardiomyopathy." (PMID 29556499, 2018). "Increased levels of TXNIP has been associated with many diseases of oxidative stress including ischemic heart disease, diabetes, cancer, AD, and PD." (PMID 30670947, 2018). "Vitamin D3 decreases diabetes-induced ROS and exerts protective effects against retinal vascular damage and cell apoptosis in association with inhibition of the ROS/TXNIP/NLRP3 inflammasome pathway." (PMID 29682582, 2018). "TxnIP is upregulated in both the diabetic kidney and the diabetic heart, and it predisposes to diabetes-associated oxidative damage." (PMID 29934664, 2018). "Our findings demonstrate that modulation of dynamic cellular calcium homeostasis and TXNIP suppression present viable pharmacologic targets to prevent cytokine-mediated beta cell loss in diabetes." (PMID 28717166, 2017). "In this study, it was found that the rs6721961 (−617C/A) polymorphism of Nrf2 gene was associated with diabetes in Mexican mestizo men, while the rs7211 polymorphism of TXNIP gene and the rs2071749 polymorphism of HMOX1 gene were associated with obesity." (PMID 27274779, 2016). "Proinflammatory and proapoptotic thioredoxin-interacting protein (TXNIP) has a causative role in the development of diabetes." (PMID 26245868, 2015). "In pancreatic islets cells, the expression of TXNIP has been shown to be increased by glucose and to promote apoptosis and potentially glucotoxicity and β-cell loss in insulin resistance and diabetes." (PMID 23691179, 2013). "TXNIP has been implicated in the processes associated with diabetes and its vascular complications." (PMID 39678047, 2024). "TXNIP is also associated with the induction of cell apoptosis via ER stress-independent pathways, including inflammasome assembly, and has been implicated in the driving β-cell apoptosis and complications in diabetes." (PMID 37834034, 2023). "It has been reported that TXNIP causes cellular oxidative stress and inflammationin diabetes." (PMID 36837498, 2023). "For example, TXNIP-mediated redox inhibition is associated with the nervous system inflammation seen in Alzheimer’s disease, and also contributes to premature death of insulin-secreting cells in patients with diabetes." (PMID 37394581, 2023). "Whole body TXNIP-deficient and β-cell-specific TXNIP knockout mice have decreased β-cell apoptosis, increased β-cell mass, elevated insulin levels, and are protected from diabetes (for review see 153)." (PMID 37008937, 2023). "As for diseases like diabetes, atherosclerosis, and neurodegenerative diseases, which were caused by overexpressed TXNIP and consequently overactive apoptotic activity, TXNIP may still be an encouraging target." (PMID 35450411, 2022). "The overexpression of TXNIP causes death of β-cells, which is a major cause of diabetes mellitus." (PMID 35722152, 2022). "Furthermore, TXNIP contributes to glycogenesis in the liver, and the relationship between TXNIP mutations and the development of diabetes and hypertension has been suggested." (PMID 35888758, 2022). "Indeed, deficiency of TXNIP led to attenuation of atherosclerosis via reduction in oxidative stress in experimental diabetes." (PMID 34829831, 2021). "In this two-stage epigenome-wide association study (EWAS), low TXNIP cg19693031 methylation is associated with high triglycerides levels independently of diabetes in contrast to a previous study reporting an association of hypertriglyceridemia and genetic variation of TXNIP in diabetes patients." (PMID 33567593, 2021). "Also, serum TXNIP content was reported to be negatively associated with peripheral nerve conduction velocity (NCV) in patients with type 2 diabetes mellitus." (PMID 34162834, 2021).
diabetes (continued). "Finally, the recent report that TXNIP levels are increased in diabetes is consistent with the enhanced susceptibility of LS patients to develop type 2 diabetes mellitus." (PMID 33182502, 2020). "Vitamin D3 decreases diabetes induced Reactive Oxygen Species (ROS) and exerts protective effects against retinal vascular damage and cell apoptosis in association with the inhibition of the ROS/TXNIP/NLRP3 inflammasome pathway." (PMID 33633656, 2020). "TXNIP serves in different cellular functions, especially in glucose metabolism and redox homeostasis, and had initially been implicated to play an important pathophysiological role in various diseases including diabetes, inflammation, and arteriosclerosis." (PMID 33081035, 2020). "Thus, TXNIP inhibition of the Trx/TrxR system causes oxidative stress, mitochondrial dysfunction, and retinal cell death in diabetes." (PMID 31649499, 2019). "Recently, TXNIP is shown to be associated with the vascular complications of diabetes." (PMID 30733849, 2019). "Diabetes strongly induces TXNIP in the retina and causes retinal cell injury and early cell death." (PMID 31355358, 2018). "In contrast, TXNIP deficiency protects against diabetes by preventing beta-cell apoptosis." (PMID 27438705, 2016). "In this regard, chronic hyperglycemia-associated TXNIP expression could potentially lead to thiol oxidation and misfolded protein accumulation in ER lumen and cause ER stress in diabetes." (PMID 22474421, 2012). "TXNIP expression is enhanced in several disease risk for AD: diabetes, hypertension, and ischemia." (PMID 22482078, 2012). "Our data point to a mechanism through which diabetes, associated with sustained ChREBP activity and increased expression of ChoRE element-containing target genes such as TXNIP in the retina, may result in loss of vision and an altered proteomic landscape of the diabetic retina." (PMID 39851533, 2025). "The TXNIP gene encodes for the thioredoxin interacting protein, which is primarily involved in inflammatory, metabolic and apoptotic processes, and plays an important role in the development of diabetes, by influencing insulin production and beta-cell apoptosis." (PMID 36791658, 2023). "Additionally, diabetes-associated genes such as TXNIP, SPON2 and PAPPA were upregulated." (PMID 33923831, 2021). "Because TXNIP is strongly associated with impaired insulin secretion and β-cell apoptosis in diabetes models, inactivation of TXNIP is being pursued clinically for both T1D and T2D treatments." (PMID 40136648, 2025). "Thioredoxin-interacting protein (TXNIP) is a stress-response gene highly induced by early diabetes and hyperglycemia." (PMID 39690856, 2025). "Thioredoxin (TXN) and thioredoxin-interacting protein (TXNIP) are reduction-oxidation signaling complex that play crucial roles in oxidative stress- and inflammation-mediated diseases, such as diabetes, autoimmune disease, cancer, and apoptosis." (PMID 40248092, 2025). "On the other hand, thioredoxin expression does not follow glucose-induced TXNIP changes but has an opposite effect to TXNIP on the progression of diabetes." (PMID 40559375, 2025). "The elucidation of the role of TXNIP in the pathogenesis of diabetes was decisive for its further investigation in its contribution to the development of GDM." (PMID 40559375, 2025). "As a cell stress regulator, the ubiquitination enhancement of TXNIP can exert protective effects in diabetes models, such as the ischemic hind limb model of diabetic mice." (PMID 39629879, 2025). "TXNIP has been extensively studied in metabolic disorders such as diabetes and obesity, where it plays a role in the apoptosis of pancreatic β cells." (PMID 40260243, 2025). "This review summarizes the published knowledge on the implications of TXNIP in apoptotic and inflammatory mechanisms in diabetes and discusses the results obtained from TXNIP studies in GDM." (PMID 40559375, 2025).